PIK3CA (phosphatidylinositol-4,5-bisphosphate 3-kinase catalytic subunit alpha)
Diseases named in the same sentence as PIK3CA in open-access papers (continued):
Sharing a sentence is not in itself a finding about the gene and the disease.
meningioma (continued). "Mutations in TRAF7, KLF4, AKT1, or PIK3CA are commonly associated with grade 1 meningioma, whereas combined mutations might be associated with a high recurrence rate." (PMID 35712491, 2022). "However, none of these mutations occurred in known cancer genes or in genes associated with meningioma besides a missense somatic mutation in PIK3CA in the tumor of patient B. Mutations in PIK3CA have been previously associated with meningioma." (PMID 34504799, 2021). "The frequency of AKT and PIK3CA mutations in NF2 wild-type meningiomas highlights a prominent role of this pathway in the pathobiology of meningiomas in general, and it is conceivable that the activation of these pathways may contribute to tumorigenesis also in NF2 mutant tumors." (PMID 38571886, 2024). "Mutations in PIK3CA and AKT1 are frequent in meningiomas, whereas activating mutations affecting the RAS/RAF/MEK/ERK, PI3K/AKT, and Wnt pathways have been described in pituitary adenomas." (PMID 41514664, 2026). "NF2 wild-type meningiomas frequently harbor mutations in TRAF7, KLF4, AKT1, PIK3CA, and SMO and are enriched in skull-base meningiomas." (PMID 38571886, 2024). "In the cohort of only CDKN2A intact/wt meningiomas, all meningiomas with PIK3CA or POLR2A mutations were CDKN2Alow cases, whereas the only meningioma with an ARID1A mutation was CDKN2Ahigh." (PMID 37093270, 2023). "Until now PIK3CA was mainly found in transitional/meningothelial meningiomas often located at the skull base, the oncogenic impact has yet to be determined." (PMID 36641486, 2023). "TRAF7 is mutated in about 20% of all meningiomas and is frequently associated with KLF4, AKT1, and PIK3CA mutations." (PMID 38137885, 2023). "Indeed, it seems reasonable to assume that at least part of the meningioma cases previously believed to be caused by yet unrecognized genetic factors might in fact contain BRAF/NF2/PIK3CA/SMO mutations at frequencies inferior to the limits of traditional detection methods." (PMID 38259646, 2023). "NF2-altered tumors are mainly localized at the convexity or in the lateral and posterior skull base; SMO-mutated meningiomas arise in the olfactory groove, while those with AKT1 and PIK3CA mutations are mostly found in the anterior and middle skull base." (PMID 35049691, 2022). "PIK3CA, PIK3R1, and AKT3 mutations similarly increase PI3K/AKT signaling and are found in ~ 20% of anterior skull base or convexity meningiomas." (PMID 34846640, 2022). "Meningioma‐relevant mutations were present in 90/126 (71.4%) specimens including NF2, TRAF7, KLF4, SMO, AKT1,TERT promotor, ARID,SUFU, and PIK3CA mutations in similar frequencies compared to previous studies." (PMID 35213082, 2022). "Noteworthy, none of the cases had gene mutations typically observed in skull base meningiomas and involving AKT1, PIK3CA and SMO, while one case had co-occurring NF2 and SMARCB1 mutations previously found in sagittal meningiomas." (PMID 35049691, 2022). "Progestine-associated meningiomas, which are generally grade 1 and 2, present NF2 alteration only in 7.5% of cases, while a PIK3CA mutation can be found in 35% of cases." (PMID 34679551, 2021). "ATK1 and PIK3CA are associated with the MTOR signaling pathway and act with TRAF7 in approximately 10–15% of all meningiomas and, interestingly, over 30% of all cancers." (PMID 34638590, 2021). "mTOR pathways, which are activated by meningiomas with ATK1 and PIK3CA mutations, are also being targeted by mTOR inhibitors everolimus and vistusertib (NCT03071874, NCT01880749)." (PMID 34638590, 2021). "Apart from NF2 alterations in sporadic meningiomas, various oncogenic mutations in KLF4, SMO, TRAF7, PIK3CA, AKT1 and POLR2A are also found to be clinically actionable genetic events in meningiomas." (PMID 34722286, 2021).
meningioma (continued). "Each subtype of meningiomas has its own molecular features, but some genetic mutations (including NF2, TRAF7, AKT1, and PIK3CA) can be found among several subtypes of meningiomas, which confuse the judgment of tumor evolution." (PMID 33014773, 2020). "In our dataset of tumours, all the SMO L412F mutant tumours were observed exclusively as convexity supratentorial tumours and meningothelial subtypes, while the PIK3CA H1047R mutant tumours were sphenoid wing meningiomas." (PMID 32070062, 2020). "PIK3CA, located on chromosome 3q26.3 encodes the p110 alpha catalytic subunit of PI3K, occurs in 7% of non-NF2 associated grade I meningiomas, and has been reported in grade 2 and grade 3 tumors." (PMID 33346248, 2020). "Among the meningiomas, the most common mutations were in NF2 (59/71), PIK3CA (22/71), FGFR3 (13/71), SMO (11/71) and AKT1 (10/71), with Tertp (1/71) mutations the least frequent." (PMID 31565188, 2019). "Recently, alterations in other oncogenic genes such as TRAF7, AKT1, KLF4, PIK3CA, SMO, and DMD have also been implicated in meningioma etiology." (PMID 31191822, 2019). "More recently, a mutation in Phosphatidylinositol 4,5-bisphosphate 3-kinase catalytic subunit alpha isoform (PIK3CA) was detected by targeted sequencing of 150 meningiomas." (PMID 31565188, 2019). "Other common driver mutations in our cohort such as CDKN2A, ARID1A, BRCA1, NF1, AKT1, SMO, PIK3CA have similarly been noted in various prior sequencing studies of meningiomas." (PMID 31191822, 2019). "Next, we focused on the most prevalent genetic alterations reported in meningiomas so far, including NF2, SMARCB1, as well as TRAF7, AKT1, SMO, KLF4, PIK3CA, and TERT in non-NF2 mutated meningiomas." (PMID 31470906, 2019). "Next, we focused on the most common genetic alterations reported so far in meningiomas, including the NF2, SMARCB1, as well as TRAF7, AKT1, SMO, KLF4, PIK3CA, and TERT in non-NF2 mutated meningiomas." (PMID 31470906, 2019). "Such an approach is now feasible in meningioma with the recent identification of AKT1, SMO, and PIK3CA mutations, which opens the door for targeted pharmacotherapeutics in ~20% of grade I meningiomas." (PMID 27458586, 2016). "Inhibitors of SMO, AKT1, and PIK3CA hold promise as molecularly targeted pharmacotherapy in meningioma." (PMID 27458586, 2016). "The present study aimed to assess the occurrence of the mutations in the EGFR TK domain and in the selected downstream genes, KRAS, BRAF and PIK3CA, in a relatively large group of meningioma patients." (PMID 24932282, 2014). "The combination of data from the previous and current studies indicates a 3.4% (3/87) frequency of PIK3CA variations in atypical and anaplastic meningiomas." (PMID 24932282, 2014). "TRAF7 mutations in meningioma co-occur either with mutations in Kruppel-like factor 4 (KLF4) or in other genes, including v-Akt murine thymoma viral oncogene homolog 1 (AKT1) or phosphatidylinositol-4,5-bisphosphate 3-kinase catalytic subunit alpha (PIK3CA) variants." (PMID 41372821, 2025). "Additional frequent genomic alterations in meningioma include mutations in TNF receptor associated factor 7 (TRAF7), KLF transcription factor 4 (KLF4), and phosphatidylInositol-4,5-bisphosphate 3-kinase catalytic subunit alpha (PIK3CA)." (PMID 39726707, 2024). "Other checkpoint proteins expressed include PD-L2 and B7-H3 in meningiomas with alterations in the PI3K/AKT/mTOR pathway genes, CTLA-4 in CD3+ T cells in atypical meningiomas with PIK3CA or smoothened, frizzled class receptor (SMO) mutations, and the cancer/testis antigen NY-ESO-1." (PMID 37366884, 2023). "Moreover, it is relevant to develop new GEMMs that explore targetable somatic mutations found in human meningiomas such as TRAF7, AKT1, and PIK3CA, among others." (PMID 38001599, 2023). "Targeting PIK3CA has long been an area of therapeutic interest given the role that increased protein expression in the PI3K/AKT pathway plays in more aggressive malignant meningiomas." (PMID 36686824, 2022).
meningioma (continued). "According to the 2021 WHO brain tumor classification scheme, convexity and the majority of spinal meningiomas have similar molecular findings (loss of chromosome 22q and/or NF2 mutations), while skull base meningiomas demonstrate different mutations (AKT1, TRAF7, SMO, and PIK3CA)." (PMID 36179256, 2022). "CREBBP, PIK3CA (R108H), PIK3R1, BRCA1, and SMARCB1 are the most represented mutations; unfortunately, none of these mutations can predict the rate of recurrence in NF2-mutated meningiomas." (PMID 35892898, 2022). "In contrast, we could not find in our WHO grade 1 tumors and control populations, non-synonymous genetic variants, for other genes previously reported to be recurrently mutated in meningiomas such as the TRAF7, AKT1, KLF4, TERT, and PIK3CA genes." (PMID 34868937, 2021). "New GEMMs are needed in order to explore targetable somatic mutations found in human meningiomas, such as TRAF7, AKT1 or PIK3CA, where they will be essential for understanding the specific biological mechanisms involved and to provide accurate tools for preclinical drug evaluation." (PMID 34359639, 2021). "Notably, the PIK3CA-mutant meningiomas lacking mutations in NF2, AKT1, and SMO, tend to express TRAF7 mutations." (PMID 35565385, 2022). "TRAF-7 mutated meningiomas demonstrated elevated levels of programmed death ligand-1 (PD-L1), the major ligand for the programmed death checkpoint pathway, while PD-L2 is highly expressed in PI3K/AKT/mTOR pathway mutations and CTLA-4 was frequently expressed in PIK3CA and SMO mutated tumors." (PMID 36033542, 2022). "In addition to the established association of meningioma with pathogenic aberrations in the tumour suppressor gene NF2, genomic analyses have identified genes including TRAF7, KLF4, AKT1, SMO, PIK3CA and POLR2A to possess recurrent mutations in low grade non-NF2 mutant meningioma." (PMID 33167358, 2020). "However, mutations in TRAF7 can be present in isolation, though often they can co-occur with KLF4, AKT1, or PIK3CA mutations, whereas mutations in SMO and POLR2A are usually mutually exclusive Interestingly, the meningiomas arising from SMO and AKT1-MTOR aberrations often arise in the skull base." (PMID 33194703, 2020). "Previous investigations have identified Wnt pathway activation across meningiomas with SSVs targeting TRAF7, KLF4, PIK3CA, POLR2A, the Hedgehog pathway, and even NF2 and SMARCB125." (PMID 39251601, 2024). "Other genetic alterations, exclusive of NF2 that are reported in sporadic adult meningiomas, include TRAF7, SMO, KLF4, AKT1 and PIK3CA." (PMID 39612013, 2024). "A second subgroup contained AKT1 (n = 26), PIK3CA (n = 14) and SMO (n = 7) mutant skull-based meningiomas, and a third mixed subgroup included 237 meningiomas with a heterogeneous spectrum of low frequency and non-recurrent alterations." (PMID 33087175, 2020). "A second subclass within this group contained AKT1 (n = 26), PIK3CA (n = 14) and SMO (n = 6) mutant meningiomas (total n = 46)." (PMID 33087175, 2020). "Inhibitors of recently identified meningioma oncogenes, including AKT1, SMO, and PIK3CA, are now in clinical trial for recurrent and progressive meningiomas." (PMID 28923059, 2017). "PIK3CA co-mutations are also found in meningiomas with TRAF7 mutations but without KLF4 mutations, and PIK3CA is also associated with activation of mTOR signaling, as with AKT1 alterations." (PMID 41372821, 2025). "In summary, mTOR pathway activation via AKT1 or PIK3CA mutations promotes cell proliferation and acts together with TRAF7 dysfunction in meningiomas without KLF4 co-mutations." (PMID 41372821, 2025).
meningioma (continued). "CDKN2A deleted meningiomas did not harbour SMARCB1, AKT1, PIK3CA, SMO, POLR2A, or RB1 somatic mutations." (PMID 37093270, 2023). "NF2 mutations were found in 44% of the cases, while common genetic alterations in meningiomas of other locations (TRAF7, AKT1, SMO, KLF4, PIK3CA, and TERT) were lacking in non-NF2-associated cases." (PMID 31470906, 2019). "Merlin-intact meningiomas can encode somatic short variants (SSVs) targeting TRAF7, PIK3CA, AKT1, KLF4, or the Hedgehog pathway, but some of these variants may be passenger mutations that do not influence meningioma tumorigenesis." (PMID 36993679, 2023). "Irrespective of the histological grade, most meningiomas (55%) exhibit NF2 alterations, while NF2 wild-type meningiomas may harbor mutations in TRAF7, KLF4, PIK3CA or SMO." (PMID 35049691, 2022). "This may be in part because the AKT1 and PiK3CA mutations are rare, found only in 9% and 7% of WHO grade 1 meningiomas without NF2 abnormalities." (PMID 36139608, 2022).
vascular malformation (61 papers, 2015 to 2026). A non-neoplastic disorder that is the result of defects of vascular morphogenesis. "Vascular malformations are anomalies of blood or lymphatic vessels that are frequently associated with activating PIK3CA mutations." (PMID 42081505, 2026). "In relation to vascular lesions, PIK3CA pathogenic somatic variants are more commonly described in low-flow vascular malformations than in AVMs." (PMID 41350447, 2025). "Aberrant activation of this pathway is strongly linked to slow-flow vascular malformations and PIK3CA-related overgrowth spectrum, and increasing evidence also implicates it in fast-flow vascular malformations." (PMID 41430313, 2025). "In our study, we analyzed PIK3CA mutations at several critical hotspots that have been implicated in various vascular malformations, including those affecting the lymphatic system." (PMID 41300578, 2025). "Pathogenic PIK3CA variants are commonly associated with oncogenesis, overgrowth, and vascular malformations." (PMID 41357804, 2025). "Gain-of-function mutations, resulting in the hyperactivation of the endothelial receptor tyrosine kinase or the PI3K alpha catalytic subunit PIK3CA, cause the formation of vascular malformations, particularly of the sporadic venous malformation type." (PMID 39728742, 2024). "A high prevalence of PIK3CA-activating mutations has been identified in the vascular malformations seen in both sporadic and familial forms of cerebral cavernous malformation." (PMID 39062925, 2024). "A recent study identified somatic LOF mutations in PIK3R1 and GOF mutations in PIK3CA that were associated with a novel vascular malformation termed capillary malformation with dilated veins (CMDV)." (PMID 38747293, 2024). "Activating mutations in the PIK3CA gene have been identified in various types of vascular malformations, including lymphatic malformations (LMs) and venous malformations (VMs)." (PMID 38201347, 2023). "While TIE2 mutations were observed only in VMs, PIK3CA mutations were observed also in LMs and combined vascular malformations: CVM, capillary malformation with dilated veins (CMDV), capillaro-lymphatico-venous malformation (CLVM), CLOVES, and KTS." (PMID 37937645, 2023). "Somatic activating gene mutations in the PIK3CA/AKT/mTOR signaling pathway result in various vascular malformations and heterogeneous clinical manifestations associated with tissue overgrowth." (PMID 34980271, 2022). "PIK3CA mutations in vascular malformations are similar to those found in epithelial cancer, being the missense mutations in the helical (PIK3CAE542K and PIK3CAE545K) and the kinase (PIK3CAH1047R) domains the most prevalent." (PMID 35695059, 2022). "We show that active angiogenesis is required for the pathogenesis of vascular malformations caused by activating Pik3ca mutations." (PMID 35695059, 2022). "The ASM mutations of the PIK3CA gene, especially in the p110α catalytic subunit, are detected in a large number of mixed vascular malformations." (PMID 36293054, 2022). "For this, we isolated and cultured ECs derived from human vascular malformations carrying mutations in PIK3CA and TEK/TIE2, together spanning the genetic causes of more than 80% of low‐flow lesions in patients." (PMID 35695059, 2022). "One of the genes identified to be mutated in vascular malformations encodes the phosphatidylinositol-4,5-bisphosphate 3-kinase catalytic subunit alpha (PIK3CA, also known as p110α)." (PMID 34112235, 2021). "Several PIK3CA somatic mutations have been shown to be oncogenic as well as function as the main pathogenic mechanisms of LMs and vascular malformations by promoting the hyperproliferation of endothelial cells." (PMID 33964933, 2021).